HDAC6 (histone deacetylase 6)
Diseases named in the same sentence as HDAC6 in open-access papers (continued):
Sharing a sentence is not in itself a finding about the gene and the disease.
lymphoma (24 papers, 2013 to 2025). A malignant (clonal) proliferation of B- lymphocytes or T- lymphocytes which involves the lymph nodes, bone marrow and/or extranodal sites. "Conversely, transcription of Bcl2 was strongly decreased in lymphoma cells after HDAC6 inhibition, which underlines the apoptotic phenotype." (PMID 36068335, 2022). "HDAC6 is also being targeted towards treatments for these leukemias and lymphomas, together with multiple myeloma and neurological diseases." (PMID 40370107, 2025). "HDACi, particularly those targeting HDAC6, have shown promise in preclinical studies for various cancers, including breast, prostate, and lymphomas." (PMID 40590021, 2025). "We isolated lymphoma B-cells from Eμ-Myc mice and treated these cells ex vivo with the HDAC6 inhibitor M-100." (PMID 36068335, 2022). "Here, we demonstrated that MYC-dependent lymphomas are extremely sensitive to the highly specific HDAC6 inhibitor M-100." (PMID 36068335, 2022). "This compound is considered a first-in-class isoform-selective HDAC6 inhibitor and is being studied for the treatment of patients with lymphoma." (PMID 34944907, 2021). "Decreased expression of miR-548m and increased expression of HDAC6 work synergistically to induce lymphoma formation and drug resistance." (PMID 33194698, 2020). "The cell-to-cell interaction between lymphoma and stromal cells induced HDAC6 expression as a result of the significant reduction of miR-548m, confirming that HDAC6 is a direct target for miR-548m." (PMID 32403283, 2020). "The HDAC6-selective inhibitor ricolinostat exerts pronounced anti-lymphoma effects both alone and in combination with the alkylating agent bendamustine, by impairing the activation of caspase 8, -9, -3, and the Bcl-2 family." (PMID 33117804, 2020). "In lymphoma cells, the overexpression of HDAC6 in primary lymphocytes and T cell lines increase cell migration in response to cytokines." (PMID 30096875, 2018). "A recent study in lymphoma, showed that HDAC6 plays an oncogenic role in DLBCL and the combination of ricolinostat with crizotinib (ALK inhibitor) generated a strong synergistic effects." (PMID 30096875, 2018). "In hematological malignancies, HDAC6 has been reported to be overexpressed in both B- and T-cell lymphomas and its inhibition has demonstrated activity in preclinical models of lymphomas and MM." (PMID 30096875, 2018). "Our study demonstrated that the HDAC6 inhibitor ricolinostat is effective in reducing lymphoma cell growth and increasing apoptosis as a single agent and the efficacy is increased by the combination with bendamustine." (PMID 28315173, 2017). "We investigated and explained the anticancer effects of an HDAC6 inhibitor, ricolinostat alone and in combination with bendamustine in lymphoma cell lines." (PMID 28315173, 2017). "Demonstration of such cytotoxic effects coupled with the improved safety profile of a selective HDAC6 inhibitor, provide the rationale for the development of this combination in the treatment of patients with lymphoma." (PMID 28315173, 2017). "Our findings identified the HDAC6 inhibitor M-100 as a new tool to target MYC-dependent lymphomas." (PMID 36068335, 2022). "For instance, the use of the HDAC6-selective inhibitor ACY1215 (also named rocilinostat or ricolinostat) as a regimen for relapsed or refractory lymphoma and MM is currently in phase I/II clinical trials [Lymphoma (NCT02091063), MM (NCT01323751, NCT01583283, NCT01997840)]." (PMID 33117804, 2020). "We thus investigated the involvement of HDAC6 in lymphoma cell growth." (PMID 25546298, 2014). "These facts suggest that selective HDAC6 inhibitors may have mild side effects, consistent with the favorable safety profile observed for the selective HDAC6 inhibitor ricolinostat in patients with relapsed/refractory lymphoma." (PMID 39063958, 2024).
lymphoma (continued). "In preclinical studies in lymphoma cell, Lwin and colleagues, revealed that tubastatin A induced apoptosis and inhibited clonogenic growth of lymphoma cells both in the absence and presence of stroma adhesion, further supporting the role of HDAC6 in cell adhesion-mediated clonogenicity." (PMID 30096875, 2018). "The same group discovered that miR-548m downregulation, and subsequent histone deacetylase 6 (HDAC6) overexpression, enhances the adhesion of NHL to lymphoma stroma cells, promoting sustained c-Myc activation." (PMID 36615316, 2022). "Our selective HDAC6 inhibitor can be further improved with medicinal chemistry efforts and future trials might be possible with a top lead compound to be explored in rare T- or NK cell leukemias/lymphomas in line with the clinical need to find less toxic and more specific drugs." (PMID 36355493, 2022). "However, ricolinostat did not cause downregulation of cyclin D1 in lymphoma cell lines, and it remains to be determined whether ricolinostat or other HDAC6 selective inhibitors being developed are effective at downregulating MYC and FGFR3 or other FGFRs." (PMID 29423038, 2018). "Accordingly, there is intense interest to develop isoform‐selective HDACi's, notably of HDAC1 and HDAC6 (and HDAC8) HDAC1 is overexpressed in a wide range of solid tumors as well as in several leukemias and lymphomas, including acute lymphoblastic leukemia (ALL), CLL and AML." (PMID 40370107, 2025). "TMU-35435 showed better inhibitory effects on total HDAC activity and isoform-specific HDAC activity, including HDAC6 activity, than did suberoylanilide hydroxamic acid (SAHA), which was the first Food and Drug Administration (FDA)-approved HDACi for the treatment of lymphoma." (PMID 31683883, 2019). "This variable expression of HDAC6 was not evident in the primary lymphoma sections." (PMID 30096875, 2018). "Furthermore, the stroma-lymphoma cell-to-cell interaction triggered a feed-forward loop of c-Myc/miR-548m, where activated c-Myc, recruited EZH2 complex (a co-repressor of miR-548m promoter) inducing a sustained reduction of miR-548m and a consequent upregulation of HDAC6." (PMID 32403283, 2020).
amyotrophic lateral sclerosis (22 papers, 2012 to 2025). Amyotrophic lateral sclerosis (ALS) is a neurodegenerative disease characterized by progressive muscular paralysis reflecting degeneration of motor neurons in the primary motor cortex, corticospinal tracts, brainstem and spinal cord. "HDAC6 is associated with familial cases of amyotrophic lateral sclerosis (ALS), in which mutations in the DNA binding protein TDP-43 result in impaired microtubule-dependent axonal trafficking of mRNAs and the formation of TDP-43 aggregates." (PMID 33041780, 2020). "Deletion of HDAC6 in a mouse model of mutant superoxide dismutase 1-linked amyotrophic lateral sclerosis is also neuroprotective, as reflected by the extended life span of mice and increased motor axon integrity." (PMID 25031639, 2014). "Further emphasizing the therapeutic potential of HDAC6 inhibitors are results demonstrating that loss of HDAC6 expression/activity is also neuroprotective in other neurodegenerative diseases, including AD, Huntington’s disease and amyotrophic lateral sclerosis." (PMID 25031639, 2014). "Interestingly, the RNA-binding modulator factors TDP-43 and FUS/TLS, whose mutations are associated with familial amyotrophic lateral sclerosis (ALS), have HDAC6 mRNA as a specific substrate." (PMID 23634874, 2013). "Interestingly, starvation-induced TDP-43, whose insoluble aggregates are associated with NDs such as amyotrophic lateral sclerosis, frontotemporal dementia (FTD), and ADs, activates autophagy in an HDAC6-dependent manner in GBM, blocking apoptosis." (PMID 39595195, 2024). "Furthermore, inhibiting HDAC6 rescues the reduced mitochondrial axonal transport and mitochondrial length in hippocampal neurons treated with Aβ, as well as in pluripotent stem cells (iPSCs) from Amyotrophic Lateral Sclerosis (ALS) patients." (PMID 31281249, 2019). "Studies examining the biology of amyotrophic lateral sclerosis (ALS) have led to a focus on HDAC6 as a putative therapeutic target." (PMID 30935091, 2019). "Furthermore, HDAC6 deletion or inhibition have been shown to be beneficial for some neurodegenerative disorders, including amyotrophic lateral sclerosis (ALS) and Charcot-Marie-Tooth disease." (PMID 36402791, 2022). "TDP-43-positive inclusions are hallmarks of frontotemporal dementia and amyotrophic lateral sclerosis (ALS), and there seems to be a lack of HDAC6 in these inclusions." (PMID 22518139, 2012).
Huntington disease (22 papers, 2011 to 2025). Huntington disease (HD) is a rare neurodegenerative disorder of the central nervous system characterized by unwanted choreatic movements, behavioral and psychiatric disturbances and dementia. "Similar findings were reported in a study targeting Huntington’s disease, where the HDAC6 inhibitor was shown to enhance tubulin acetylation, stabilize microtubules, and improve axonal transport." (PMID 41274966, 2025). "Actually, HDAC6 inhibition compensates transport deficits in Huntington’s disease promoting kinesin-1 recruitment by increasing microtubule acetylation." (PMID 34458961, 2021). "In animal experimental models of PD and Huntington’s diseases, HDAC6 inhibition rescues axonal transport defects and is beneficial for the neuronal survival." (PMID 32655357, 2020). "The genetic deletion of the histone deacetylase 6 exacerbates cognition deficits in the Huntington's disease mouse model, but reducing HDAC6 ameliorates cognitive deficits in an AD mouse model." (PMID 33040050, 2020). "In the postmortem striatum of Huntington’s disease patients, a dramatic decrease was observed in levels of acetylated α-tubulin, a major substrate of HDAC6, suggesting a microtubule-based transport deficit in this disease." (PMID 26790818, 2016). "Inhibition of HDAC6 has been shown to be protective in Huntington's disease (HD)." (PMID 23184605, 2013). "The inhibition of the Histone Deacetylase 6 (HDAC6) increases tubulin acetylation, thus stimulating intracellular vesicle trafficking and brain-derived neurotrophic factor (BDNF) release, that is, cellular processes markedly reduced in Huntington’s disease (HD)." (PMID 26445700, 2015).
neuroblastoma (20 papers, 2011 to 2025). Neuroblastoma (NB) is the most common solid, extracranial childhood tumor. "Decreased phosphorylation levels of c-Jun have also been observed in glioblastoma cells following inhibition of HDAC6, which is additionally implicated in neuroblastoma tumorigenesis and metastatic dissemination." (PMID 33117806, 2020). "In summary, our study supports using selective HDAC inhibitors as targeted antineoplastic agents and underlines the therapeutic potential of selective HDAC6/8/10 inhibition in high-grade neuroblastoma." (PMID 29947893, 2018). "Silencing HDAC6 directly causes severe cytoskeletal rearrangements and loss of neurite outgrowth in human neuroblastoma SH-SY5Y cells." (PMID 21878116, 2011). "To test the impact of α-tubulin acetylation on α-synuclein oligomerization, we used the selective HDAC6 inhibitor Tubacin to induce α-tubulin acetylation in a neuroblastoma SK-N-SH cell line overexpressing human wild-type α-synuclein (SK-N-SH Syn+, )." (PMID 37569662, 2023). "Butyrate treatment has been shown to upregulate the expression of both HDAC11 (in bovine cell cultures and seabass liver) and HDAC6 (in mouse neuroblastoma and microglia cell cultures)." (PMID 32344633, 2020). "We have previously demonstrated that inhibition of HDAC6/10 using tubastatin A results in intracellular accumulation of doxorubicin and thus enhances neuroblastoma cell death upon combination treatment." (PMID 33121173, 2020). "Compound 6b dose-dependently induces the acetylation level of α-tubulin via inhibition of HDAC6 in human neuroblastoma SH-SY5Y cell line." (PMID 31835389, 2019). "Using tubastatin A as a positive control, we showed that caspase-3/7 activation following HDAC6-selective C1A treatment of two neuroblastoma cell lines was inhibitor type and concentration dependent." (PMID 30318510, 2018). "Here, we introduce TH34 (3-(N-benzylamino)-4-methylbenzhydroxamic acid), a novel HDAC6/8/10 inhibitor for neuroblastoma therapy." (PMID 29947893, 2018). "Additionally, HDAC6 is also thought to contribute to neuroblastoma tumorigenesis through regulating Bax-dependent apoptosis via deacetylation of Ku70 and regulation of the interaction between Ku70 and Bax." (PMID 33117806, 2020). "In neuroblastoma, inhibition of HDAC6 can enhance cell adhesion and impair both polarization and efficient migration, which correlates with findings that HDAC6 expression is upregulated at metastatic sites, such as the mediastinum, abdominal cavity, and pelvic cavity." (PMID 33117806, 2020). "Similarly, HDAC6/10 inhibition increased accumulation of doxorubicin in two other neuroblastoma cell lines, IMR-32 and SK-N-AS." (PMID 29968769, 2018). "Finally, we investigated the effect of a combined inhibition of HDAC6, 8 and 10 in short-term cultures of primary neuroblastoma cells isolated from a MYCN-amplified INSS stage 4 tumor of a 1-month-old patient (NB8)." (PMID 29947893, 2018). "Inhibition of HDAC6 with tubacin also led to a failure to degrade misfolded protein aggregates in murine neuroblastoma cells, very likely due to impaired retrograde transport of autophagic vacuoles and lysosomes, and LC3 recruitment to the autophagosomes membrane was impaired." (PMID 25915736, 2015). "In the human neuroblastoma SH-SY5Y cell line, the HDAC6 inhibitor was observed to induce an increase in the acetylation level of α-tubulin by inhibiting HDAC6 in a dose-dependent manner." (PMID 39650725, 2024). "Ku70 and Bax have previously been shown to interact in neuroblastoma cells, with Ku70 acetylation regulated by the CBP acetyl transferase and HDAC6 leading to Bax release and induction of apoptosis." (PMID 37957138, 2023). "The functional activity of the chemical probe CM-695 against its targets (HDAC class I, PDE9 and HDAC6) was assessed in vitro, in SH-SY5Y neuroblastoma cells." (PMID 31281249, 2019).
neuroblastoma (continued). "During the first 24 h of treatment with the HDAC6/8/10 inhibitor TH34, we detected a marked increase in γH2AX foci, providing strong evidence of the involvement of HDACs 6, 8 and 10 in DNA damage repair mechanisms in neuroblastoma." (PMID 29947893, 2018). "Immunofluorescence staining of γH2AX indicated nuclear foci in TH34-, but not solvent-treated high-grade neuroblastoma cells, confirming dose-dependent occurrence of DSBs under HDAC6/8/10 inhibition." (PMID 29947893, 2018). "Thiol-based HDAC6 inhibitors, such as compound St.24, underscored notable potency and selectivity with potentially improved pharmacokinetics, while sulfur-containing derivatives like compound St.28 showed HDAC8 selectivity and in vivo antitumor efficacy in neuroblastoma models." (PMID 41440016, 2025). "Furthermore, a specific thiazolidinedione-based histone deacetylase 6 inhibitor (HDAC6I) has been shown to normalize the abundance of acetylated alpha microtubule proteins and reverse METH-induced morphological changes in neuroblastoma cell lines." (PMID 39650725, 2024). "To this hypothesis, we measured Tau acetylation in protein extracts from neuroblastoma cells treated with the selective Hdac6 inhibitor Tubastatin A (TubA), combined or not with the proteasomal inhibitor MG-132 treatment." (PMID 36393857, 2022). "HDAC6 expression does not significantly correlate with prognostic markers in neuroblastoma." (PMID 29947893, 2018). "Likewise, in neuroblastoma cells, treatment with tubacin, which also specifically inhibits HDAC6 catalytic activity, did not result in an accumulation of AVOs, indicating that autophagic flux was not blocked under nutrient-rich and proteasome-active conditions." (PMID 25915736, 2015). "However, given that HDAC6 is not significantly correlated to prognostic markers in neuroblastoma and its inhibition is well tolerated in preclinical and clinical studies, even a triple-acting inhibitor could exert the same favourable impact, without many side effects." (PMID 36077415, 2022). "In conclusion, the selective HDAC6/8/10 inhibitor TH34 effectively and selectively eliminates high-grade neuroblastoma cells while sparing non-transformed human cells." (PMID 29947893, 2018).
non-small cell lung carcinoma (20 papers, 2012 to 2024). A group of at least three distinct histological types of lung cancer, including non-small cell squamous cell carcinoma, adenocarcinoma, and large cell carcinoma. "In present study, we demonstrated that the nuclear translocation frequency of HDAC6 is associated with distant metastasis and overall survival in patients with non-small cell lung cancer (NSCLC)." (PMID 26388610, 2015). "In this study, we found that a low frequency of nuclear HDAC6-positive cells in tumors was associated with distant metastasis and a worse overall survival in 134 patients with non-small cell lung cancer (NSCLC)." (PMID 26388610, 2015). "Previous studies have reported that USP10 promotes cisplatin resistance by deubiquitinating HDAC6 in non-small cell lung cancer, and promotes tumor growth and proliferation by deubiquitinating TAZ/YAP in liver cancer." (PMID 38321024, 2024). "For instance, the E3 ubiquitin ligase HDAC6 orchestrates the ubiquitination degradation of Chk1, thereby modulating the cell cycle and subsequently influencing radiosensitivity in non-small-cell lung cancer (NSCLC)." (PMID 38137461, 2023). "And Histone deacetylase 6 (HDAC6) acted as a metastasis supporter induced the Wnt/β-catenin signaling pathway by suppressing TMEM100 expression in non-small cell lung cancer (NSCLC)." (PMID 35928881, 2022). "Knockdown of HDAC6 enhances cisplatin-induced DNA damage in non-small cell lung cancer cells." (PMID 36951571, 2023). "Our published tissue microarray data also demonstrates that HDAC6 is upregulated across all three subtypes of non-small cell lung cancer (NSCLC), the second most commonly diagnosed cancer across both sexes that is responsible for the greatest number of cancer-related deaths annually." (PMID 33020410, 2020). "The high expression HDAC6 has been suggested to promote the proliferation of lung adenocarcinoma cells, and HDAC6 inhibitors have been considered as effective anticancer agents against non-small cell lung cancer." (PMID 32917017, 2020). "This phenomenon might be due to activation of the ATR-CHK1 pathway, as additional research has shown that HDAC6 depletion increases cisplatin-induced cytotoxicity by activating the ATR/CHK1 pathway in non-small cell lung cancer." (PMID 30594243, 2018). "Pemetrexed/sildenafil (P/S) cotreatment also increased autophagy in non-small cell lung carcinoma (NSCLC) cells (A549) via an induction of CerS6 (ceramide synthase 6) expression and the disruption of HDAC6 content." (PMID 31861179, 2019).